H2BC9 (H2B clustered histone 9)
Description:
Core component of nucleosome. Nucleosomes wrap and compact DNA into chromatin, limiting DNA accessibility to the cellular machineries which require DNA as a template. Histones thereby play a central role in transcription regulation, DNA repair, DNA replication and chromosomal stability. DNA accessibility is regulated via a complex set of post-translational modifications of histones, also called histone code, and nucleosome remodeling.
Synonyms: H2B/j; H2BFJ; HIST1H2BH
Tractability: PROTAC: UniProt records ubiquitination sites on it; ubiquitination databases record sites on it.
Gene: Protein-coding gene on chromosome 6 (26,251,614 to 26,252,075, forward strand). Ensembl gene ENSG00000275713.
Subcellular location: Nucleus; Chromosome
Subcellular location (Human Protein Atlas): Nucleoplasm; Cytosol
Pathways (Reactome):
Gene expression (Transcription): B-WICH complex positively regulates rRNA expression; DNA methylation; ERCC6 (CSB) and EHMT2 (G9a) positively regulate rRNA expression; MLL4 and MLL3 complexes regulate expression of PPARG target genes in adipogenesis and hepatic steatosis; NoRC negatively regulates rRNA expression; PRC2 methylates histones and DNA; RNA Polymerase I Promoter Escape; RNA Polymerase I Promoter Opening; RUNX1 regulates genes involved in megakaryocyte differentiation and platelet function; RUNX1 regulates transcription of genes involved in differentiation of HSCs; Regulation of endogenous retroelements by KRAB-ZFP proteins; Regulation of endogenous retroelements by Piwi-interacting RNAs (piRNAs); Regulation of endogenous retroelements by the Human Silencing Hub (HUSH) complex; SIRT1 negatively regulates rRNA expression; Transcriptional regulation by small RNAs
Chromatin organization: CHD1 and CHD2 subfamily; CHD6, CHD7, CHD8, CHD9 subfamily; ChAHP complex assembly; HATs acetylate histones; HDACs deacetylate histones; Interaction of NuRD complexes with transcription factors; NuRD complex assembly
DNA Repair: Cleavage of the damaged purine; Cleavage of the damaged pyrimidine; Nonhomologous End-Joining (NHEJ); Processing of DNA double-strand break ends; Recognition and association of DNA glycosylase with site containing an affected purine; Recognition and association of DNA glycosylase with site containing an affected pyrimidine; Recruitment and ATM-mediated phosphorylation of repair and signaling proteins at DNA double strand breaks
Cell Cycle: Condensation of Prophase Chromosomes; Deposition of new CENPA-containing nucleosomes at the centromere; G2/M DNA damage checkpoint; Inhibition of DNA recombination at telomere; Packaging Of Telomere Ends
Developmental Biology: Activation of anterior HOX genes in hindbrain development during early embryogenesis; Chromatin modifications during the maternal to zygotic transition (MZT); Replacement of protamines by nucleosomes in the male pronucleus; Transcriptional regulation of granulopoiesis
Disease: Defective pyroptosis; Dengue Virus-Host Interactions
and 18 more pathways
Gene Ontology:
Molecular function: enzyme binding; protein binding; STAT family protein binding; ubiquitin-like protein ligase binding; DNA binding; structural constituent of chromatin; protein heterodimerization activity
Biological process: antibacterial humoral response; antimicrobial humoral immune response mediated by antimicrobial peptide; chromatin organization; innate immune response in mucosa; nucleosome assembly
Cellular component: extracellular exosome; nucleus; protein-containing complex; nucleoplasm; nucleosome; chromosome
Genetic constraint (gnomAD): Loss-of-function variants: 11 observed, 6.04 expected, observed/expected ratio (o/e) 1.82, 90% interval 1.04 to 1.96. That is too few expected variants to judge how well the gene tolerates losing a copy. Missense variants: 219 observed, 177.17 expected, observed/expected ratio (o/e) 1.24, 90% interval 1.11 to 1.38. Synonymous variants: 136 observed, 77.12 expected, observed/expected ratio (o/e) 1.76, 90% interval 1.53 to 1.96.
Homologues: Orthologues: chimpanzee H2BC9 (100% identical), rat Hist2h2be (98% identical). Paralogues in human: H2BC10 (99% identical), H2BC17 (99% identical), H2BC18 (99% identical), H2BC4 (99% identical), H2BC6 (99% identical), H2BC7 (99% identical), H2BC8 (99% identical), H2BC12 (98% identical), H2BC15 (98% identical), H2BC21 (98% identical), H2BC5 (98% identical), H2BC11 (98% identical), and 9 more.
Diseases named in the same sentence as H2BC9 in open-access papers:
H2BC9 is named in the same sentence as 20 diseases in open-access papers, as found by Europe PMC text mining. Sharing a sentence is not in itself a finding about the gene and the disease. The quoted sentences say what the papers report.
cervical cancer (3 papers, 2017 to 2023). A primary or metastatic malignant neoplasm involving the cervix. "H2BC9, which belongs to the H2B aggregator histone gene family, is commonly recognized as a molecular biomarker and an independent prognostic factor for H2BC9 cervical cancer in cervical cancer and glioma." (PMID 37035196, 2023). "Several studies have shown that H2BC5, H2BC9, and H2BC11 are independent prognostic factors of cervical cancer, and H2BC12 is an independent prognostic factor for low-grade glioma." (PMID 36387186, 2022).
glioma (2 papers, 2022 to 2023). A benign or malignant brain and spinal cord tumor that arises from glial cells (astrocytes, oligodendrocytes, ependymal cells). "H2B family genes, especially H2BC5 and H2BC9, as molecular biomarkers, have high specificity and sensitivity for the prognosis of glioma patients, and are significantly correlated with glioma grade, age and other factors, showing a high research potential." (PMID 36387186, 2022). "Univariate and multivariate Cox analysis showed that H2BC5, H2BC9, H2BC11, and H2BC21 are high-risk factors for glioma." (PMID 36387186, 2022). "First, we used the ssGSEA algorithm to assess immune cell infiltration in gliomas and found that H2BC9 and H2BC11 were positively correlated with influx of macrophages, Th2 cells, neutrophils and eosinophils." (PMID 36387186, 2022). "In particular, high H2BC5, H2BC9, H2BC11, and H2BC21 expression was associated with poor glioma prognosis." (PMID 36387186, 2022). "In summary, H2BC5, H2BC9, H2BC11, and H2BC21 were independent prognostic indicators of glioma, and H2BC9 and H2BC11 may correlate with tumor immunity." (PMID 36387186, 2022). "This study used multiple algorithms to assess the correlation between H2B gene expression and immune cell infiltration and found that H2B family genes, especially H2BC9 and H2BC11 are closely related to the immune system of glioma patients." (PMID 36387186, 2022). "Kaplan-Meier survival analysis showed that high expression of H2BC5, H2BC9, H2BC11, and H2BC21 correlated with a poor OS, DFS, and PFI of glioma patients." (PMID 36387186, 2022). "The methylation status of H2BC5, H2BC9, H2BC11, and H2BC21 in different glioma cohorts was evaluated in the Methsurv database." (PMID 36387186, 2022). "Enrichment analysis of H2BC5, H2BC9, H2BC11, and H2BC21 was also conducted to understand how the H2B gene is involved in the pathological progression of glioma." (PMID 36387186, 2022). "Expression of H2BC5, H2BC9, H2BC11, and H2BC21 was higher in glioma tissues." (PMID 36387186, 2022). "Besides, The algorithm of the estimate package showed that the expression of H2B family genes, especially H2BC9, H2BC11 and H2BC12 was positively correlated with the presence of stromal cells in glioma, the level of immune cells and the purity of tumor cells." (PMID 36387186, 2022). "Collectively, these data indicated that H2BC5, H2BC9, H2BC11, and H2BC21 could independently predict glioma prognosis." (PMID 36387186, 2022). "The analysis of H2B family gene expression in glioma showed that H2BC5, H2BC9, H2BC11, and H2BC21 can be used as independent predictive factors for glioma prognosis, and overexpression of H2BC9 and H2BC11 may lead to tumor deterioration through the immune system." (PMID 36387186, 2022). "Moreover, the ROC curve showed that H2BC5, H2BC9, H2BC11, and H2BC21 all had meaningful predictive power for glioma, especially H2BC9 and H2BC11, which showed excellent sensitivity and specificity in predicting the survival of glioma patients, with an area under the curve (AUC) of >0.8." (PMID 36387186, 2022).
lung adenocarcinoma (2 papers, 2022 to 2023). A carcinoma that arises from the lung and is characterized by the presence of malignant glandular epithelial cells. "Among them, low expression of C12orf56, DLX5, DSC3, FEZF1, GSTA1, H2BC9, IGSF11 and high expression of EREG, CEACAM6, SLC34A2 in lung adenocarcinoma were found to predict poor prognosis for patients." (PMID 37035196, 2023).
astrocytoma (1 paper, 2022). "The GSE4271 and GSE4412 datasets were used as a supplement to the results and suggested the prognostic value of H2BC5, H2BC9, H2BC21 on astrocytoma." (PMID 36387186, 2022).
lung squamous cell carcinoma (1 paper, 2023). "Ten prognostic beneficial factors of the heterogeneous expression of lung squamous cell carcinoma genes driven by TTN mutations were screened for and DLX5, FEZF1, H2BC9, EREG, and SLC34A2 were identified as the main factors of the prognostic models." (PMID 37035196, 2023).
cancer (5 papers, 2019 to 2025). A tumor composed of atypical neoplastic, often pleomorphic cells that invade other tissues. "The protein network of unique cancer cell genes in the “cancer cells_vs_all-PDAC” group exhibited top 10 hub genes, including H4C6 (HIST1H4A or HIST1H4C), MYC, H3C12 (HIST1H3A or HIST1H3D), DDX21, USP7, RFC4, APEX1, CDK9, H2BC9 (HIST1H2BH), and NOP2." (PMID 40906153, 2025).
tumor (4 papers, 2021 to 2022). "On the other hand, H2BC9 and H2BC11 were inversely associated with pDC cells, which promoted the recruitment of regulatory T cells into the tumor microenvironment and resulted in immunosuppression and tumor growth." (PMID 36387186, 2022). "H2BC9 and H2BC11 positively correlate with the immune checkpoint PDCD1, which mediates inhibitory pathways that are exploited by tumors to mitigate antitumor immunity and escape destruction by the immune system, thereby promoting tumor survival." (PMID 36387186, 2022).
H2BC9 also shares sentences with these, for which no sentence is quoted: multiple myeloma (2 papers); rheumatoid arthritis (2); systemic lupus erythematosus (2); viral infection (2); autoimmune disease (1); breast tumors (1); endometrial cancer (1); herpes simplex infection (1); HIV-1 infection (1); immune system diseases (1); non-small cell lung carcinoma (1); osteoporosis (1); Rahman syndrome (1).